POLD1 (DNA polymerase delta 1, catalytic subunit)
Diseases named in the same sentence as POLD1 in open-access papers (continued):
Sharing a sentence is not in itself a finding about the gene and the disease.
tumor (continued). "Interestingly, molecular studies of the tumours revealed an ultra-mutated tumour phenotype with mutational signatures of both PMS2 and POLD1, suggesting that these factors interacted to cause the relatively severe clinical phenotype in these cases." (PMID 36895471, 2023). "In summary, these results demonstrated that POLD1 is potentially engaged in the regulation of immune interactions and may assist tumor immune escape." (PMID 37047824, 2023). "Our current preliminary mechanism exploration indicated that POLD1 may create a tumor immunosuppressive microenvironment and inhibit the susceptibility to ferroptosis leading to a poor prognosis." (PMID 37047824, 2023). "In addition, POLD1 expression was significantly upregulated in HCC tumor when compared with the corresponding liver tissue in TCGA RNA-seq dataset (fold change = 3.15, p < 0.0001) and in our in-house RNA-seq dataset (fold change = 3.26, p < 0.0001)." (PMID 35865168, 2022). "In addition to the absence of other known actionable driver mutations, NTRK+ CRC tumors harbor very high tumor mutation burden (median 53 mut/MB), with most of them being microsatellite instability‐high (MSI‐H), and an enrichment of POLE/POLD1 mutations." (PMID 35506567, 2022). "Importantly, POLD1 expression was associated with immune checkpoint molecules, including CD274, CD80, CD86, CTLA4, PDCD1 and TCGIT, and facilitated an immune-excluded tumor microenvironment." (PMID 34868924, 2021). "For example, POLE/POLD1 gene mutations are associated with microsatellite instability (MSI), mismatch repair (MMR), and TMB, and CMTM6 is related to PD-L1 expression and regulation of anti-tumor immunity." (PMID 34790698, 2021). "We speculate that this may be because POLD1 is involved in DNA cleavage repair, which affects the tumor microenvironment." (PMID 34868924, 2021). "Next, we generated a multivariate Cox proportional hazards (CPH) model that included the expression levels of POLD1 and RAD51 and other common clinical prognostic factors (patient age, KPS group, tumor size, extent of resection, IDH mutational status, and MGMT promotor methylation status)." (PMID 34771522, 2021). "Therefore, regardless of how technically robust biomarkers such as MSI/MSS status, TMB, PDL1, POLE/POLD1 mutation, and MSI-like gene signature, these biomarkers will only characterize the quantity of tumor-infiltrating CD8+ T cells." (PMID 34594218, 2021). "To extend our in vitro data we next used a murine xenograft tumor model to assess the sensitivity of POLD1+/+ and POLD1R689W/- cells to the ATR inhibitor AZD6738 in vivo, as this inhibitor showed the strongest proliferation inhibitory effects in the in vitro experiments." (PMID 33144657, 2020). "NGS and IHC analyses of the tumor revealed multiple defects in DDR genes and proteins, specifically, heterozygous truncating mutations in CHK1, FANCM, RAD50, POLD1, and FANCP; compound heterozygous truncating mutations in ARID1A; and loss of ATM and ARID1A protein by IHC." (PMID 32568634, 2020). "We had available WES data obtained from four other MMR proficient CRC tumors that did not present germline or tumor alterations in POLE or POLD1 to compare their number of substitutions and mutational spectrum with our POLE mutant." (PMID 28423643, 2017). "POLE and POLD1 are not classical tumour suppressor genes, as loss-of-function mutations appear not to be pathogenic." (PMID 23447401, 2013). "Moreover, some APC mutations that are generally rare in CRCs are relatively common in POLE- and POLD1-mutant tumours, an example being the Arg1114X change." (PMID 23447401, 2013). "Notably, co-mutations with PBRM1, a tumor suppressor, enhance ICI efficacy in POLD1-mutated tumors." (PMID 40661943, 2025). "Moreover, the tumor of patient 1 with a POLD1 mutation had no POLE mutation associated signature but conversely the POLD1 mutation associate signature." (PMID 39233831, 2024).
tumor (continued). "We speculated that the high expression of POLD1 could perturbate the tumor microenvironment of RCC." (PMID 37047824, 2023). "Finally, depletion of POLD1 also inhibited tumor growth in the xenograft mouse model." (PMID 37047824, 2023). "We discovered that DNA polymerase (POLD1) pedigree mutations might be a risk factor for BLCA and that patients with POLD1G178R mutations tended to have higher tumor mutation burden (TMB), immune cell invasion, and longer survival times than patients with POLD1 wild-type BLCA6." (PMID 37105989, 2023). "Tumour 3 harboured a POLD1 mutation but this was subclonal and could not explain the presence of clonal signature 14 mutations." (PMID 31949146, 2020). "Therefore, downregulation of these DDR genes e.g., RAD51C, LIG1 and POLD1-3 may produce synergies towards formation of persistent unrepairable complex DSB in tumor cells treated with dual combination leading to cell growth arrest and lethality." (PMID 30042828, 2018). "Unique molecular characteristics have been described in neoplasms from defective DNA repair-related polyposis involving the MUTYH, NTHL1, MBD4, MSH3, POLE and POLD1 genes and the MMR genes in CMMRD." (PMID 40237887, 2025). "Contributions of signatures associated with MMRD (SBS6, SBS15 and SBS26) and concurrent defects in the exonuclease domain of POLE and POLD1 (SBS14 and SBS20) were found in the CMMRD tumors, depending on the affected gene and tumor type." (PMID 39031223, 2024). "Both tumors were reported as MSS from clinical testing and were hypermutated (POLD1/POLH tumor- 12.85 mut/Mb, POLE tumor- 14.44 mut/Mb)." (PMID 37095444, 2023). "To investigate the role of POLD1 in the carcinogenesis and metastasis of BLCA in vivo, we established a tumor-bearing model by subcutaneous injection and a lung metastasis model by tail vein injection in NOID/SCID mice." (PMID 37105989, 2023). "Lastly, POLD1 expression positively correlated with the immune infiltration levels of B cells, macrophages, dendritic cells, and CD4+ T cells in the HCC tumor microenvironment." (PMID 36980791, 2023). "They observed that low POLD1 expression, found in more than half of CRC cases, was correlated with larger tumor size, adenocarcinoma histology, and stage III tumors." (PMID 36980791, 2023). "Overexpression of POLD1 promoted HCC progression potentially through accelerating cell-cycle and improving tolerance of tumor cells to DNA damage." (PMID 35189839, 2022). "HE staining showed that the tumor tissue of the RSV group had obvious necrosis, while the RSV + POLD1-OE group had less fibrous tissue than the RSV group." (PMID 33747905, 2021). "Further animal experiments showed that compared to the control group, the final tumor volume and wet weight of the RSV and RSV + POLD1-OE groups were smaller." (PMID 33747905, 2021). "The list of genes with stringently tumor-specific hypermethylation includes, for instance, ERCC1, MGMT, POLD1, and RBBP8/CtiP." (PMID 29445424, 2018). "Core promoters with adjacent regions of the human genes CDC6, POLD1, CKS1B,MCM2, and PLK1 were cloned into a pGL3 vector in front of the Photinus pyrailsgene Luc in order to study the tumor specificity of the promoters." (PMID 24303203, 2013). "Despite loss of heterozygosity of the wild-type allele in the tumor, suggesting a haploinsufficient state, this case lacked POLD1-specific signatures (e.g., SBS10c/d), indicating MMR dominance over POLD1’s contribution." (PMID 40661943, 2025). "Notably, the A2 tumor area exhibited significant reductions in proteins essential to the DNA replication pathway, including MCM3, MCM4, POLD1, RFC2, and PCNA, all of which are pivotal for maintaining the integrity of DNA replication." (PMID 40076915, 2025). "Using previously identified iron‐interacting proteins to compare the individual genes in these two pathways, we noticed that the gene expression of cyclin dependent kinase 1 (CDK1) and POLD1 were decreased 4.02‐ and 4.31‐fold by DFO in tumor colonoids, respectively." (PMID 36703617, 2023).
tumor (continued). "POLD1 expression levels in the tumor cells did not correlate with clinicopathological factors and the prognosis of CRC patients (data not published yet)." (PMID 36980791, 2023). "POLE and POLD1 are currently not considered classical tumor suppressor genes, and LOH is typically not observed in tumors." (PMID 37095444, 2023). "Furthermore, although the tumours we originally described in POLE and POLD1 carriers were microsatellite-stable, the frequency of MSI (12.5%) that we now describe in CRCs is similar to that in sporadic CRCs, despite the earlier onset of the former." (PMID 33948826, 2022). "When comparing vehicle- and AZD6738-treated POLD1+/+ tumors, we observed virtually no discernible differences in tumor growth, with both quintupling their original tumor size during treatment." (PMID 33144657, 2020). "BER, MMR, FA, and DNACHK mutations as well as mutations in POLE/POLD1 were only significantly associated with longer overall survival in unadjusted analyses, but not after adjustment for TMB or tumor type." (PMID 32676589, 2020). "Among others, polymerase delta (POLD1) methylation was enriched in 24 out of 32 different tumor types, implying an essential role in DNA repair or tumor suppression independent of tumor entity." (PMID 29445424, 2018). "In humans, some, but not all, tumours from patients with germline POLE or POLD1 mutations show LOH, although data on other forms of ‘second hit’ are lacking in these tumours." (PMID 23447401, 2013). "POLD1-mutant tumors may also foster an immune-excluded tumor microenvironment (TME), characterized by the presence of immune cells in the tumor stroma but limited infiltration into the tumor bed." (PMID 40661943, 2025). "Moreover, we have also demonstrated that the level of POLD1 immunoexpression in tumor cells does not correlate with the demographic and clinicopathological characteristics of ccRCC patients." (PMID 36980791, 2023). "Particularly, to explore the association between POLD1 expression and ccRCC patients, we used five GEO expression profiling by array RNA sequencing profiles from the TCGA and ICGC databases containing ccRCC tumor and non-tumor specimens." (PMID 37047824, 2023). "In addition, studies on POLE/POLD1 mutations have not been extended to all tumor types, and there are relatively few studies on the morphological and immunohistochemical expression rates of POLE/POLD1-mutated tumors." (PMID 35780178, 2022). "Whether these aspects of DNA polymerase function are important for tumour development is unknown, as is the explanation for the near-absence of somatic POLD1 EDMs." (PMID 23447401, 2013). "The criteria for potential treatment beyond MMR/MSI testing and POLE/POLD1 are unclear, but data from the NICHE trial suggest that immunotherapy may have the potential for complete response in dMMR tumours and at least partial response in some pMMR tumours with higher levels of CD8+ T cells." (PMID 34694371, 2021). "POLE and POLD1 may not to act as classical tumor suppressor genes." (PMID 24583393, 2014). "We propose that TMB instead may be a good surrogate biomarker for MSI, as a range of 30–80 mut/Mb is typically seen in MSI tumours, as opposed to MSS POLE/POLD1 tumours, which typically have greater than 150 mut/Mb." (PMID 32306292, 2020).
infection (4 papers, 2020 to 2025). The state of being infected such as from the introduction of a foreign agent such as serum, vaccine, antigenic substance or organism. "The upregulation of ACVR1 and the suppression of POLD1 upon H. pylori infection establish a connection between the infection, genomic instability, and the development of gastric carcinogenesis." (PMID 39924917, 2025). "In the meantime, the host–pathogen interaction proteome offered insight into the major proteins involved in immunity of C. curvignathus (Nubp1, Cyp6a13, GTP1-1p, and POLD1) and M. anisopliae pathogenesis (Sec8, Hsp78, Catp, Lias, and RNAh) throughout the infection process." (PMID 33806225, 2021). "However, as the infection progressing, their expressions showed a decreasing pattern, except for POLD1, which increased at 24 h and 48 h, before dropping at 96 h PI." (PMID 33806225, 2021). "The protein levels of NTHL1, MUTYH, FEN1, RAD51, POLD1, and LIG1 were observed to be decreased, during the infection, in a CagA- and phospho-CagA-related manner in both cell lines." (PMID 33339161, 2020). "Our study showed that infection can promote an imbalance between APE1 and the downstream proteins of LP-BER FEN1, POLD1, and LIG1." (PMID 33339161, 2020). "REV3 silencing did not affect viral accumulation in local infection assays, in sharp contrast to POLD1 or POLD2 silencing, indicating that DNA polymerase ζ is not required for geminiviral replication." (PMID 33986276, 2021). "Our data suggest that the accessory components (RFC2, RFC3, RFC5, PCNA), polymerases (POLD1, POLD2, POLD3, POLE, POLE2, POLE4), and ligase LIG1, were downregulated during infection, for which the downregulation of RFC5, POLD1, POLD2, POLD3, POLE, and LIG1 was CagA-related." (PMID 33339161, 2020).
POLD1 also shares sentences with these, for which no sentence is quoted: meningioma (3 papers); skin cancer (3); astrocytoma (2); Cowden disease (2); familial melanoma (2); genetic disorder (2); hyperplastic polyp (2); hypertriglyceridemia (2); juvenile polyp (2); juvenile polyposis syndrome (2); mandibular hypoplasia (2); medulloblastoma (2); pneumonitis (2); renal carcinoma (2); tumor syndrome (2); uterine carcinosarcoma (2); acquired lipodystrophy (1); adenocarcinoma (1); aging (1); atherosclerosis (1); Atypical progeroid syndrome (1); autosomal dominant disease (1); bladder urothelial carcinoma (1); brain cancer (1); café-au-lait macules (1); colitis (1); colon adenocarcinoma (1); colon polyps (1); colonic adenomatous polyps (1); COVID-19 (1).
A further 48 diseases each share a sentence with POLD1 in 1 paper.